GPR37 (G protein-coupled receptor 37)
Diseases named in the same sentence as GPR37 in open-access papers (continued):
Sharing a sentence is not in itself a finding about the gene and the disease.
tumor (continued). "Furthermore, we demonstrated that GPR37 impedes tumor progression and enhances sensitivity to radiation in ESCC." (PMID 39730361, 2024). "While GPR37 overexpression might contribute to tumor progression, it also underscores its protective role in stress-related cellular processes." (PMID 39633709, 2024). "Furthermore, we identified the presence of GPR37 protein within exosomes, which has the potential to modulate the development and radioresistance of recipient tumor cells." (PMID 39730361, 2024). "Univariate and multivariate analyses showed that low protein level of GPR37 was linked to tumor stage, lymph node metastasis, and vascular or nerve invasion, but not to patient sex, age, or tumor size index." (PMID 39730361, 2024). "This increase may reflect a tumor self-regulatory mechanism aimed at reducing inflammation by increasing GPR37 expression, facilitating adaptation to hypoxia, and enhancing invasiveness." (PMID 39633709, 2024). "Consequently, further in‐depth research on GPR37 will not only help reveal the development mechanism and tumor drug resistance mechanism of NSCLC but also use GPCR as a drug target to provide a theoretical basis for individualized treatment options for NSCLC." (PMID 37732632, 2023). "GPR37 knockdown was found to act a tumor‐suppressor role in NSCLC and could be used as a potential therapeutic target in NSCLC." (PMID 37732632, 2023). "The effect of GPR37 on the regulation of tumor cell sensitivity to cisplatin was observed by FACS." (PMID 37732632, 2023). "GPR37 expression levels were analyzed in pan-tumor tissues and their normal counterparts." (PMID 37837549, 2023). "Moreover, the study demonstrated that the expression of GPR37 was lower in normal alveolar epithelial cells than that in different tumor cell lines." (PMID 37732632, 2023). "GPR37 was previously identified as the receptor of Parkin, an E3 ubiquitin ligase encoded by PARK2, involved in ubiquitination and proteasome mediated degradation/clearance of misfolding proteins, which is closely related to tumor development." (PMID 37837549, 2023). "In patients with low household income, demethylation of GPR37 and subsequent increased expression as found in our study might lead to elevated β-adrenergic stress signaling and immunosuppression in the tumor microenvironment." (PMID 37101222, 2023). "The study explored the influence of GPR37 on tumor cell proliferation." (PMID 37732632, 2023). "Several studies have shown a detrimental role of GPR37 in promoting tumor growth." (PMID 36430912, 2022). "Xenograft tumor assay demonstrated that Exo-GPR37 could also inhibit ESCC proliferation in vivo." (PMID 39730361, 2024). "Thus, the precise function of GPR37 contingent upon the tumor type." (PMID 39730361, 2024). "Furthermore, we examined the effects of GPR37 on tumor cell apoptosis and invasion." (PMID 37732632, 2023). "Moreover, GPR37 can lead to the transition of cell morphology to mesenchymal‐like cells, promote cell migration, invasion, and metastasis, and at the same time make tumor cells more resistant to drugs, which is consistent with the previous outcomes of this study." (PMID 37732632, 2023). "They showed that GPR37 was able to bind to CDK6, which in turn induced cell cycle arrest to promote tumor progression in LUAD58." (PMID 38584220, 2024). "In TCGA, significant differences were observed in the expression levels of SERPINH1 and GPR37 between normal tissues and LUAD tumor tissues." (PMID 39052154, 2024). "The expression of CDK1, ECT2, GJB2, GPR37, GPX2, and GPX8 gene was up-regulated in the tumor group (p < 0.001), whereas the expression of TLR4 was down-regulated in the tumor group (p < 0.001) when compared with those in the normal group." (PMID 37689745, 2023).
tumor (continued). "CDK1, ECT2, EZH2, GJB2, GPR37, GPX2, and GPX8 mRNA expression was up-regulated in the tumor group (p < 0.001), whereas GPX3, HYAL1, and TLR4 mRNA expression was down-regulated in the tumor group (p < 0.001) compared with those in the normal group." (PMID 37689745, 2023). "Conversely, we observed that GPR37 knockdown suppresses NSCLC cell invasion, migration, and proliferation, promotes cell apoptosis, increases sensitivity to cisplatin, and affects tumor formation and growth." (PMID 37732632, 2023). "This showed that GPR37 knockdown can inhibit the PI3K/Akt/mTOR signal transduction pathway and tumor occurrence and development." (PMID 37732632, 2023).
cancer (14 papers, 2014 to 2025). A tumor composed of atypical neoplastic, often pleomorphic cells that invade other tissues. "G protein-coupled receptor 37 (GPR37) is a member of GPCR, also known as parkin-associated endothelin receptor-like receptor, which has been studied in cancer as well." (PMID 33364431, 2021). "In addition to the physiological and pathophysiological roles already outlined, changes in GPR37 expression have been associated with both cancer and epigenetic regulation." (PMID 26635605, 2015). "Mechanistically, NPD1 or ARU binding to GPR37 in macrophages promotes the release of IL-10, which further inhibits cancer-induced osteoclastogenesis." (PMID 39965073, 2025). "Post-surgical immunohistochemical assessment of GPR37 expression in resected cancer tissue will enable the stratification of ESCC patients." (PMID 39730361, 2024). "In this review, we discuss the beneficial and detrimental roles of GPR37 in neurons, glial cells, cancer cells, and immune cells." (PMID 36430912, 2022). "REG4 can interact with transmembrane CD44, G protein-coupled receptor 37, mannan and heparin on cancer cells." (PMID 36172286, 2022). "GPR37 agonists also protect against cancer-induced bone destruction." (PMID 39965073, 2025). "In addition, western blot and qRT-PCR analyses on five pairs of ESCC and adjacent non-cancerous tissues confirmed that both protein and mRNA expression of GPR37 were significantly lower in cancer tissues." (PMID 39730361, 2024). "Indicated that GPR37 may exhibit different mechanisms in different cancers." (PMID 37732632, 2023). "Additionally, GPR37 expression is lower in cancer and is a prognostic indicator." (PMID 36052170, 2022). "Hence, one can see that GPR37 may be a double-edged sword in cancer, but its function in LUAD is rarely known." (PMID 33364431, 2021). "Interestingly, GPR37 expression was inversely proportional to the histopathological grading of the cancer and Kaplan–Meier survival analysis of patients indicated that those with “low” GPR37 expression had markedly reduced survival time (n = 37 vs. 20 “high” GPR37 expressers)." (PMID 26635605, 2015). "Additionally, Reg4 expression was up-regulated by caudal type homeobox 2 (CDX2), which further enhanced cancer cell migration and adhesion through the activation of SRY-related high-mobility group box 9 (SOX9) and G-protein-coupled receptor 37 (GPR37)." (PMID 39857608, 2024). "For the other receptors of this subgroup, information relative to their implication in cancer is rare (one report for GPR37) or lacking." (PMID 24662753, 2014). "The role of SYT2, SCN4A, GPR37, and F2 in cancers has not been well studied." (PMID 36110953, 2022). "Moreover, direct activation of GPR37 in dorsal root ganglion (DRG) neurons and the spinal dorsal horn reduces action potential firing and the frequency of spontaneous excitatory postsynaptic currents (sEPSCs), thereby suppressing cancer-induced neuronal hyperexcitability." (PMID 39965073, 2025).
neurodegenerative disease (7 papers, 2016 to 2025). A disorder of the central nervous system characterized by gradual and progressive loss of neural tissue and neurologic function. "Further longitudinal studies combining CSF ecto-GPR37 with reliable biomarkers for neurodegenerative diseases are needed." (PMID 33637132, 2021). "Three of the genes, GPR37, MAPT and PSENEN observed interacting with all three BPA, E2, and NRF1 are associated with neurodegenerative disease." (PMID 27983596, 2016). "Three of the common E2 and NRF1 target genes, GPR37, MAPT, and PSENEN are associated with neurodegenerative disease." (PMID 27983596, 2016). "It is known that GPR37 encodes a G protein-coupled receptor (GPCR) that may play an important role in neurodevelopment and neurodegenerative diseases." (PMID 39052154, 2024). "The vertebrate G protein-coupled receptors 37 and 37-like 1 (GPR37 and GPR37L1) were discovered more than two decades ago, and they have been implicated in various neurological and neurodegenerative diseases, as well as in inflammatory pain and tumorigenesis [...]." (PMID 37047695, 2023). "GPR37 gene, a common Cd/E2/NRF1 gene, is associated with neurodegenerative disease." (PMID 27983596, 2016).
neurological disorders (7 papers, 2021 to 2025). "GPR37, also known as parkin-associated endothelin-like receptor (Pael-R), was cloned in 1997 and is highly expressed in the brain and implicated in neurological disorders such as Parkinson’s disease and autism." (PMID 33731716, 2021). "As mechanistic understanding of GPR37 deepens, interest has turned toward its utility as a biomarker in neurological disorders, particularly Parkinson’s disease (PD)." (PMID 40822851, 2025). "Since osteocalcin regulates autophagy and anxiety‐like behavior, exploring the OCN/GPR37 signaling pathway is important for understanding the pathophysiological processes of neurological disorders." (PMID 39252492, 2024). "Myelin alterations and the OCN/GPR37 signaling pathway may be two good targets for further elucidating the osteocalcin‐related pathological progression of different neurological diseases." (PMID 39252492, 2024). "Second, GPR37 has different functions in different neurological diseases." (PMID 39252492, 2024). "Targeting GPR37 may lead to novel therapeutics for treating inflammation, infection, pain, and neurological diseases." (PMID 36430912, 2022). "Thus, GPR37 appears to be protective against the demyelination that occurs in various neurological diseases." (PMID 36430912, 2022). "Therefore, GPR37 may be involved in multiple neurological diseases." (PMID 36430912, 2022).
infection (6 papers, 2021 to 2025). The state of being infected such as from the introduction of a foreign agent such as serum, vaccine, antigenic substance or organism. "Recent studies have demonstrated that GPR37 is expressed by macrophages and confers protection against infection by bacteria and parasites." (PMID 36430912, 2022). "Collectively, these data indicate that NPD1 confers protection against infection and septic death in a GPR37-dependent manner." (PMID 33731716, 2021). "infection, and Gpr37−/− mice exhibited significant hypothermia at later stages in the disease (day 17, P < 0.0001, vs. WT mice)." (PMID 33731716, 2021). "First, we measured bacterial load in peritoneal fluid (PF) from WT or Gpr37−/− mice 24 h after infection with L.m." (PMID 33731716, 2021). "Thus, GPR37 agonists can be developed for the management of acute and chronic pain after infections." (PMID 36430912, 2022). "Thus, we propose that NPD1 and other GPR37 agonists could be utilized to treat acute and chronic pain conditions post-infection as well as in other clinical contexts (e.g., neuropathic pain)." (PMID 33731716, 2021). "Activation of GPR37 in macrophages by NPD1 and ARU could promote macrophage phagocytosis to fight against these infections." (PMID 36430912, 2022). "Moreover, given that ARU can suppress infection-induced pain within 1 h of treatment, it is also possible that ARU directly inhibits pain through actions on GPR37 in peripheral sensory neurons, which is an intriguing future direction." (PMID 33731716, 2021). "Critically, adoptive transfer of macrophages primed with GPR37 activators was sufficient to decrease signatures of infection and septic death, and these effects were abolished in mice lacking GPR37." (PMID 33731716, 2021). "Furthermore, GPR37 promotes the resolution of inflammatory pain and infection-induced pain, as the duration of pain after tissue injury and infection is prolonged in mice lacking Gpr37." (PMID 36430912, 2022). "Notably, NPD1 was shown to potently reduce inflammatory pain and neuropathic pain in mice, and we also showed that ARU-priming of macrophages could promote pain resolution after post-infection, and ARU treatment itself could rapidly alleviate pain after bacterial infection through GPR37." (PMID 33731716, 2021). "Finally, the adoptive transfer of ARU-primed pMΦ also reversed L.m.-induced mechanical allodynia in Gpr37−/− mice, and intraplantar injection of ARU (100 μg) partially reversed the infection-induced mechanical allodynia in WT but not Gpr37−/− mice." (PMID 33731716, 2021).
bacterial infection (4 papers, 2021 to 2022). "NPD1 has been shown to confer protection against bacterial infections, and furthermore, this protection is mediated by GPR37 and macrophages." (PMID 36430912, 2022). "Consistently, GPR37−/− mice display enhanced mechanical and cold allodynia, as well as thermal hyperalgesia during bacterial infections, while macrophages primed with GPR37 agonists reduce mechanical allodynia in the same GPR37−/− mice." (PMID 34456731, 2021). "Interestingly, ARU treatment rapidly reduced pain after bacterial infection, which is GPR37-mediated." (PMID 36430912, 2022).
brain disorder (1 paper, 2021). A disease affecting the brain or part of the brain. "The differential diagnostic value of GPR37 in PD and AD may be useful for discriminating combined neurodegenerative pathologies, thus allowing correct stratification of these brain disorders, especially at early stage." (PMID 33637132, 2021).
GPR37 also shares sentences with these, for which no sentence is quoted: multiple sclerosis (3 papers); Huntington disease (2); parasite infection (2); Tremor (2); viral infection (2); acute encephalopathies (1); amyotrophic lateral sclerosis (1); behavioral disorders (1); bladder cancer (1); brain tumor (1); breast tumor (1); corticobasal syndrome (1); diabetes (1); disc degeneration (1); endometrial cancer (1); epilepsy (1); esophageal squamous cell carcinoma (1); glioblastoma (1); injury (1); melanoma (1); metabolic syndrome (1); myocardial infarction (1); neurotoxicity (1); oligodendroglioma (1); pancreatic cancer (1); prion disease (1); progressive supranuclear palsy (1); psoriasis (1); psychiatric diseases (1); stomach cancer (1).